DKK1 (dickkopf Wnt signaling pathway inhibitor 1)
Diseases named in the same sentence as DKK1 in open-access papers (continued):
Sharing a sentence is not in itself a finding about the gene and the disease.
osteoarthritis (16 papers, 2010 to 2026). A noninflammatory degenerative joint disease occurring chiefly in older persons, characterized by degeneration of the articular cartilage, hypertrophy of bone at the margins and changes in the synovial membrane. "Modulating the detrimental effects of DKK1 has emerged as an effective approach for preventing bone loss associated with estrogen deficiency, excessive glucocorticoid exposure, and osteoarthritis-related joint damage." (PMID 38773377, 2024). "Genes associated with DDH and osteoarthritis include FRZB, CX3CR1, ASPN, DKK1, PDRG1, GDF5, UQCC1, and TGF-β1." (PMID 41019141, 2025). "DKK-1 blockade reverses both the bone-destructive pattern of an inflammatory arthritis model and the bone-forming pattern of osteoarthritis, whereas DKK-1 blockade promotes ankylosis of sacroiliac joints in an experimental model." (PMID 28153008, 2017). "The current study demonstrates that the mRNA expression of GREM1, FRZB and DKK1 is inversely correlated with the level of cartilage degeneration in osteoarthritis." (PMID 24286177, 2013). "In contrast to the upregulation with inflammation induced by TNF-α, Dkk1 is downregulated in ankylosing spondylitis and osteoarthritis." (PMID 21438671, 2011). "We further analyzed the correlation between the plasma and synovial fluid levels of Dkk-1 and the severity of osteoarthritis." (PMID 21062498, 2010). "In the realm of osteoarthritis therapy, our research focused on the role of DKK1 in OA joints, revealing increased vascularity and expression of angiogenic factors and proteinases in synovial tissues from OA patients, alongside elevated DKK1 levels." (PMID 38773377, 2024). "Dkk-1 suppression was found to improve osteoarthritis in a mouse model in a recent report." (PMID 34868573, 2021). "In this study, we investigated whether factors implicated in osteoarthritis or regulation of chondrocyte hypertrophy influence GREM1, FRZB and DKK1 expression levels." (PMID 24286177, 2013). "Interestingly, DKK1 supplementation has recently been shown to protect from experimental osteoarthritis." (PMID 24286177, 2013). "Based on these observations, we hypothesized that the expression of GREM1, FRZB and DKK1 is inversely correlated with osteoarthritis and their expression is influenced by established regulators of chondrocyte hypertrophy." (PMID 24286177, 2013). "GREM1, FRZB and DKK1 mRNA expression were strongly decreased in osteoarthritis." (PMID 24286177, 2013). "Since osteoarthritis is associated with deregulated hypertrophic differentiation in at least a subset of patients, we hypothesized that GREM1, FRZB and DKK1 mRNA expression levels are downregulated in osteoarthritis." (PMID 24286177, 2013). "Changes in Dkk1 expression may be responsible for many of the differences in radiological appearance between osteoarthritis and rheumatoid arthritis." (PMID 21438671, 2011). "Additional investigations will be required to shed light on the possible role of Dkk-1 involved in the pathogenesis of chronic degenerative joint disorder, with the aim of developing effective pharmacological agents to delay the progression to osteoarthritis." (PMID 21062498, 2010). "Similarly decreased DKK1 levels are found in synovial fluid of animal models of osteoarthritis." (PMID 24286177, 2013). "Therefore, expression of Dkk-1 in inflammatory and degenerative joint diseases may block bone formation within the joint." (PMID 21062498, 2010). "Our research describes for the first time the perioperative changes observed in serum DKK1 and SOST levels of osteoarthritis (OA) patients undergoing TJA." (PMID 28953627, 2017). "Since in osteoarthritis development we found that FRZB was lost starting in grade 2, while DKK1 started to decrease in grade 1, we decided to test in our model if FRZB was able to prevent WNT activity when DKK1 expression was lost." (PMID 29165387, 2017).
osteoarthritis (continued). "Together, the current study demonstrates an inverse correlation between osteoarthritis and GREM1, FRZB and DKK1 gene expression in cartilage and provides insight into the underlying transcriptional regulation." (PMID 24286177, 2013).
cholangiocarcinoma (15 papers, 2020 to 2025). A carcinoma that arises from the intrahepatic biliary tree (intrahepatic cholangiocarcinoma) or from the junction, or adjacent to the junction, of the right and left hepatic ducts (hilar cholangiocarcinoma). "Furthermore, the DKK1/CKAP4 pathway upregulates the expression of plasmalemma vesicle-associated proteins in cholangiocarcinoma cells, which is positively linked to angiogenesis in various tumors." (PMID 40394415, 2025). "Surprisingly, DKK1 functions through the DKK1/CKAP4/PI3K pathway to augment the expression of plasmalemma vesicle-associated protein in cholangiocarcinoma cells, which is positively linked to angiogenesis in various tumors, hence also making this pathway a prospective anti-angiogenic target." (PMID 35355709, 2022). "Some studies have shown that sporadic cholangiocarcinoma is related to the Wnt/β-catenin signaling pathway associated with DKK-1, whereas primary sclerosing cholangitis associated cholangiocarcinoma is primarily related to inflammation-related cytokine and chemokine pathways." (PMID 33921232, 2021). "Studies have shown that DKK1 expression is elevated in cholangiocarcinoma tissues compared to normal bile duct tissues." (PMID 38730642, 2024). "As reported, Plvap can promote angiogenesis in cholangiocarcinoma through the DKK1/CKAP4/PI3K pathway, and maintain the ultrastructure and function of chorionic capillaries in retinal ECs." (PMID 39010027, 2024). "DKK1 expression was significantly higher in cancer tissues with cholangiocarcinoma (CHOL), ESCA, HNSC, LIHC, lung squamous cell carcinoma (LUSC), and STAD than that in their respective adjacent normal tissues." (PMID 34899842, 2021). "Additionally, in bioinformatics analyses of gene expression data sets in intrahepatic (iCCA) and extrahepatic (eCCA) cholangiocarcinomas, DKK1 was identified alongside MMP7 as a distinguishing marker between these cancer types." (PMID 39236081, 2024). "We found that in mice with cholangiocarcinoma, inhibiting DKK1 reduced tumour growth." (PMID 35924447, 2023). "To support evidence from our in vivo models, we assessed whether DKK1 might recruit FOXP3 regulatory T cells in human iCCA by analysing transcriptomic Illumina beadchip array data from 104 cholangiocarcinomas (GSE26566)." (PMID 35924447, 2023). "In cholangiocarcinoma, PLVAP is upregulated through a DKK1/CKAP4/PI3K‐Akt axis, correlates with micro‐vessel density and poor prognosis." (PMID 41431249, 2025). "Studies have demonstrated that DKK1 expression is often elevated in HCC and cholangiocarcinoma, promoting tumour proliferation, migration, and invasion." (PMID 41142820, 2025). "Umbilical cord MSCs enhance metastasis and chemoresistance in cholangiocarcinoma, although MSC-secreted dickkopf-related protein 1 (DKK-1), a soluble WNT antagonist, can decrease the proliferation rate of leukemia cancer cells." (PMID 39418131, 2024). "Furthermore, the monoclonal antibody DKN-01, which targets DKK1, was evaluated in combination with gemcitabine and cisplatin in a phase I clinical trial in patients with HCC and cholangiocarcinoma (NCT02375880)." (PMID 41142820, 2025).
glioblastoma (14 papers, 2010 to 2025). The most malignant astrocytic tumor (WHO grade IV). "DKK1 knockdown significantly reduced the proliferation of glioblastoma cell lines by inhibiting the PI3K–AKT pathway." (PMID 36418306, 2022). "High expression of DKK1 significantly promoted the proliferation of glioblastoma cell lines; CCK-8 experiments also confirmed the same conclusion." (PMID 36418306, 2022). "In this study, we found a unique function of SMARCC2 in inhibiting the progression of glioblastoma by targeting the DKK1 signaling axis." (PMID 36418306, 2022). "In their study, promoter methylation of DKK1 was quite rare in lower-grade astrocytoma but frequent in glioblastoma." (PMID 34064046, 2021). "U251 cells have the highest levels of DKK-1 expression in both of the culture medium and cell lysate, while glioblastoma cell lines SKMG-4 and UW-28 have the lowest DKK-1 levels in the culture medium and cell lysate, respectively." (PMID 21029453, 2010). "LncEPAT was reported to be a functional oncogene in glioblastoma, and lncEPAT silencing increased the expression of cell aging-associated genes, such as CDKN1A, CLUSTERIN, and DKK1, indicating that lncEPAT exerts a repressive function in glioblastoma cell senescence." (PMID 38228673, 2024). "In glioblastoma cancer stem cells (GBM CSCs), Ascl1 has been shown to bind a site near the Wnt antagonist gene Dkk1, whose regulation mediates Ascl1 activity in these cells." (PMID 25189209, 2014). "ASCL1 has been shown to promote WNT signalling by directly repressing DKK1, a negative regulator of WNT signalling, and synergising with WNT3A to induce active WNT signalling in glioblastoma stem cells." (PMID 41287940, 2025). "In glioblastoma cell lines UW-28, SKI-N2, and SF295, DKK-1 mRNA expression was relatively lower as compared with other glioblastoma cells." (PMID 21029453, 2010). "Overall, this study shows that SMARCC2, as a tumor suppressor, inhibits the proliferation of glioblastoma by targeting the transcription of the oncogene DKK1 through chromatin remodeling, indicating that SMARCC2 is a potentially attractive therapeutic target in glioblastoma." (PMID 36418306, 2022). "Our study showed that SMARCC2 could significantly inhibit the PI3K/AKT pathway in glioblastoma cell lines by targeting DKK1, therefore, targeting DKK1 degraders and PI3K/AKT pathway inhibitors may be a new idea for the clinical treatment of glioblastoma." (PMID 36418306, 2022). "DKK-1 could only be detected in 12 human glioblastoma cell lines, not in a panel of other tumor and normal cell lines." (PMID 21029453, 2010). "Next, we characterized the negative correlation between the expression of DKK1 and SMARCC2 in different glioblastoma cell lines by western blotting." (PMID 36418306, 2022).
liver fibrosis (14 papers, 2014 to 2025). "The results showed that the collagen deposition and liver fibrosis caused by S. japonicum infection were markedly alleviated after DKK1 treatment, which was accompanied by a decrease in the expression of α-SMA/Acta2, desmin and Col1a1." (PMID 28331224, 2017). "Liver fibrosis was exacerbated when exogenous Wnt3a was introduced, but was alleviated when Wnt signalling was suppressed by DKK1, accompanied by the reduced expression of TGF-β and CTGF in hepatocytes." (PMID 28331224, 2017). "The results showed that the over expression of Wnt3a exacerbates liver fibrosis, and intervention with DKK1 ameliorates the liver fibrosis." (PMID 28331224, 2017). "We investigated the effects of DKK1 on schistosomiasis-induced liver fibrosis as a result of the suppression of Wnt signalling through injection of Lv-DKK1-EGFP 4 or 6 weeks after S. japonicum infection." (PMID 28331224, 2017). "DKK1 is an antagonist of Wnt pathway that promotes liver fibrosis by enhancing HSCs activation." (PMID 34234100, 2021). "In this study, we hypothesize that EZH2‐mediated suppression of Dkk1 may promote hepatic fibrosis by activating Wnt/β‐catenin pathway." (PMID 28332284, 2017). "Therefore, we established a lentiviral vector loaded with either Wnt3a mRNA or Dkk1 mRNA and used them as transfected viruses to investigate the effects of the canonical Wnt pathway on schistosomiasis-induced liver fibrosis." (PMID 28331224, 2017). "Numerous studies have shown that DKK1 plays a critical role in fibrosis diseases and could serve as a potential therapeutic target in fibrotic diseases, including pulmonary fibrosis, renal fibrosis, liver fibrosis and systemic sclerosis." (PMID 37859694, 2023). "Furthermore, the addition of mesenchymal stromal cells could repair fibrosis in the lungs caused by radiation due to Dkk-1’s ability to block Wnt/β-catenin induced EMT and adenoviral overexpression of Dkk-1 can block liver fibrosis in a BDL mouse liver model." (PMID 37476157, 2023). "For instance, as a canonical inhibitor of Wnt signaling, Dickkopf1 (DKK1) was previously shown to be secreted by MSCs to ameliorate tissue injury and reduce liver fibrosis." (PMID 38529014, 2024). "In a carbon tetrachloride-induced liver fibrosis mice model, IGFBP-3 and DKK1/3 generated from AMSCs prevented the activation of hepatic stellate cells by suppressing the Wnt/β-catenin signaling pathway, decreasing liver fibrosis in mice." (PMID 37711653, 2023). "This study aimed to assess whether EMT occurs in patients with AE infection and to determine if DKK1-mediated inhibition of intrahepatic Wnt/β-catenin signaling can attenuate EMT and reduce AE-induced hepatic fibrosis." (PMID 40496021, 2025).
pancreatic ductal adenocarcinoma (14 papers, 2011 to 2026). An infiltrating adenocarcinoma that arises from the epithelial cells of the pancreas. "DKK1 was associated with pancreatic ductal adenocarcinoma prognosis in a Kaplan–Meier survival analysis with log‐rank test." (PMID 33639034, 2021). "In addition, Liu advocated that DKK1 is an independent predictor of overall survival in patients with pancreatic ductal adenocarcinoma (PDAC), associated with lymph node metastasis and T stage classification as well." (PMID 31830954, 2019). "Clinically, DKK1- and CKAP4-positive patients with pancreatic ductal adenocarcinoma have shorter 5-years survival and relapse-free survival than DKK1- or CKAP4-negative patients." (PMID 35355709, 2022). "For example, screening from the GSE15417, GSE16515, and GSE28735 pancreatic ductal adenocarcinoma and normal pancreatic tissue microarray datasets revealed that DKK1 was downregulated in pancreatic ductal adenocarcinoma compared with normal tissues." (PMID 33639034, 2021). "Simultaneous expression of DKK1 and CKAP4 is associated with poor prognosis in pancreatic ductal adenocarcinoma (PDAC), lung adenocarcinoma and squamous cell carcinoma, and esophageal squamous cell carcinoma (ESCC) patients." (PMID 34117362, 2021). "RNA sequence analysis revealed that expression of the transcription factor forkhead box M1 (FOXM1) and its target genes concordantly fluctuated with expression of DKK1 in pancreatic ductal adenocarcinoma (PDAC) cells." (PMID 34117362, 2021). "At the very least, the upregulation of Wnt activity mediated by GATA6 dependent repression of DKK1 further supports the view that GATA6 is an oncogene in pancreatic ductal adenocarcinoma." (PMID 21811562, 2011). "DKK1 is also involved in pancreatic ductal carcinoma and is a potential biomarker." (PMID 33661942, 2021). "This study found a super-enhancer enriched with abnormally active histone modifications in pancreatic ductal adenocarcinoma (PDAC), called DKK1-super-enhancer (DKK1-SE)." (PMID 39107271, 2024). "Patients with HNSCC, LUAD, BRCA, KIRP, pancreatic ductal adenocarcinoma (PAAD), LIHC, and STAD who had high DKK1 levels had shorter survival times." (PMID 38376441, 2024).
periodontitis (14 papers, 2015 to 2025). An acute or chronic inflammatory process that affects the tissues that surround and support the teeth. "The osteocytic Dkk-1 deletion reduced bone loss, mitigated inflammation, and enhanced bone formation in mice submitted to ligature-induced periodontitis." (PMID 31921182, 2019). "In animal experiments, an increase in sclerostin-positive osteocytes within alveolar bone was linked to a decrease in bone formation in a mouse model of periodontitis; in parallel, the administration of sclerostin- and DKK1-specific antibodies markedly improved alveolar bone volume and structure." (PMID 33308247, 2020). "Here, we tested the hypothesis that osteocytic Dkk-1 is a key factor in the pathogenesis of periodontitis-induced alveolar bone loss (ABL)." (PMID 31921182, 2019). "However, to date, there is no substantial evidence regarding the actual origin and role of Dkk-1 in the bone loss related to periodontitis." (PMID 31921182, 2019). "Wnt signaling, due to its well-established role in bone homeostasis and periodontal tissues regulation, as well as its inhibitors DKK-1 and sclerostin have recently shown potential as therapeutic targets for periodontitis." (PMID 38541234, 2024). "Sclerostin and DKK1 act as the Wnt signaling inhibitors and are upregulated in patients with chronic periodontitis." (PMID 36297683, 2022). "Emerging evidence demonstrated that DKK1, an antagonist of Wnt/β-catenin signaling, suppressed bone formation and contributed to inflammation in periodontitis." (PMID 34227646, 2021). "The sclerostin content in gingival crevicular fluid from chronic periodontitis patients markedly exceeds that of healthy subjects, and the protein levels of sclerostin and DKK1 in gingival biopsy tissue and serum are relatively increased." (PMID 33308247, 2020). "It has been previously reported by our group and others, that during periodontitis, there is an increase of Dkk-1 in the periodontal tissue." (PMID 31921182, 2019). "In summary, within the limits of this study, our findings emphasize the role of osteocytes in periodontitis, demonstrating for the first time that Dkk-1 secreted by osteocytes is essential for periodontal bone loss." (PMID 31921182, 2019). "Evaluation of SOST and DKK-1 in chronic periodontitis patients showed that both of these inhibitors were up-regulated in the periodontal tissues of these subjects (Napimogaet al., 2014)." (PMID 31031968, 2019). "Currently there are hints that periodontitis in gingival tissues increases Sost and Dkk-1 expression." (PMID 31921831, 2019). "This was confirmed by the reduced expression of TNF and IL-1β in the gingiva of animals with specific-deletion of Dkk-1 in osteocytes submitted to periodontitis." (PMID 31921182, 2019). "High serum levels of DKK1 have been reported in patients with pathologies related to bone resorption, including RA and periodontitis." (PMID 31703715, 2019). "It was documented that SOST and DKK1 were upregulated in the periodontal tissues of chronic periodontitis subjects, suggesting a possible role of these molecules on periodontal tissues." (PMID 27257912, 2016). "Therefore, our results also provide valuable evidence supporting the existing data regarding the correlation of DKK-1 with the severity of periodontitis." (PMID 38541234, 2024). "Additionally, the elevated protein expression observed in gingival tissue and serum of patients with chronic periodontitis, suggests that DKK-1 is the main member of the dickkoff family that inhibits the Wnt pathway in PD." (PMID 38319382, 2024). "Also, the correlation of DKK-1 with PD as a clinical parameter of periodontitis in patients with statin therapy in our study is significant; that is, the greater the PD, the higher the level of DKK-1." (PMID 38541234, 2024). "Inflammation is a major trigger for bone loss, and our data show that the lack of Dkk-1 in osteocytes during periodontitis resulted in less inflammatory infiltrates." (PMID 31921182, 2019).